KLHL10 (kelch like family member 10)
Description:
May be a substrate-specific adapter of a CUL3-based E3 ubiquitin-protein ligase complex which mediates the ubiquitination and subsequent proteasomal degradation of target proteins during spermatogenesis.
Synonyms: FLJ32662; SPGF11
Tractability: Small molecule: it belongs to a druggable protein family.
Gene: Protein-coding gene on chromosome 17 (41,835,685 to 41,848,384, forward strand). Ensembl gene ENSG00000161594.
Subcellular location: Cytoplasm
Subcellular location (Human Protein Atlas): Mid piece
Gene Ontology:
Molecular function: protein binding; ubiquitin-like ligase-substrate adaptor activity
Biological process: proteasome-mediated ubiquitin-dependent protein catabolic process; protein ubiquitination
Cellular component: Cul3-RING ubiquitin ligase complex; cytoplasm
Genetic constraint (gnomAD): Loss-of-function variants: 11 observed, 49.1 expected, observed/expected ratio (o/e) 0.22, 90% interval 0.14 to 0.37. The upper end of that interval is the gene's LOEUF score, 0.37, which puts it in group 1 of 6, group 1 being the genes least tolerant of losing a copy. Missense variants: 475 observed, 830.85 expected, observed/expected ratio (o/e) 0.57, 90% interval 0.53 to 0.62. Synonymous variants: 254 observed, 294.48 expected, observed/expected ratio (o/e) 0.86, 90% interval 0.78 to 0.96.
Homologues: Orthologues: chimpanzee KLHL10 (99% identical), macaque KLHL10 (99% identical), pig KLHL10 (99% identical), mouse Klhl10 (99% identical), rat Klhl10 (99% identical), dog KLHL10 (99% identical), rabbit KLHL10 (99% identical), guinea pig KLHL10 (98% identical), zebrafish klhl10b.2 (55% identical), zebrafish klhl10b.1 (55% identical), zebrafish klhl10a (54% identical), Drosophila melanogaster klhl10 (44% identical), and 2 more. Paralogues in human: KLHL2 (33% identical), KLHL20 (33% identical), KLHL3 (32% identical), KLHL28 (32% identical), KLHL1 (31% identical), KLHL17 (31% identical), KLHL12 (30% identical), KLHL5 (30% identical), KLHL4 (30% identical), KLHL18 (29% identical), KEAP1 (29% identical), IPP (28% identical), and 42 more.
Diseases named in the same sentence as KLHL10 in open-access papers:
KLHL10 is named in the same sentence as 8 diseases in open-access papers, as found by Europe PMC text mining. Sharing a sentence is not in itself a finding about the gene and the disease. The quoted sentences say what the papers report.
male infertility (5 papers, 2018 to 2025). The inability of the male to effect fertilization of an ovum after a specified period of unprotected intercourse. "Regarding KLHL10, there is limited information about its function, and there are no studies that associate it with cancer or any other pathology; to date, it has been related only to spermatogenesis and male infertility, and this is the first time that this gene has been associated with ALL." (PMID 36428851, 2022). "SPATA3 interacts with KLHL10, which is expressed exclusively in spermatids, and its inactivation leads to the disruption of spermiogenesis and complete male infertility in mice." (PMID 36899892, 2023). "At the moment, only three autosomal dominant genes are moderately linked to isolated male infertility: doublesex and mab-3 related transcription factor 1 (DMRT1), kelch like family member 10 (KLHL10) and synaptonemal complex protein 3 (SYCP3)." (PMID 30865283, 2019). "Remarkably, the transcripts encoding genes such as ZMYND15, KLHL10, TDRD1, TSSK2 and DNAJB13, which are linked to male infertility in other species, were differentially expressed among the treatments." (PMID 30697164, 2018).
Azoospermia (2 papers, 2021 to 2025). Absence of any measurable level of sperm,whereby spermatozoa cannot be observed even after centrifugation of the semen pellet. "Indeed, if mutations in KLHL10 imply an evolution from oligozoospermia to azoospermia, this could impact the care proposed to such patients and their relatives." (PMID 33809228, 2021).
Infertility (2 papers, 2020 to 2025). "Haploinsufficiency of KLHL10 causes infertility in male mice devoid of ES due to failure of RS elongation after step 8 precisely similar morphology observed in our KI model." (PMID 32478068, 2020). "Mutations in KLHL10 gene have been associated with oligospermia in some infertile males." (PMID 32478068, 2020).
oligospermia (2 papers, 2017 to 2020). Decreased number of spermatozoa in the semen. "Eight genes among 817 genes (0.01%) (ADAM32, DYNLRB2, KLHL10, RIMBP3C, SEPT12, TIMD4, TSACC and TTC25) were common between MArrest and teratospermia, and three genes among 435 genes (0.007%) (HRASLS, LIMS3 and MRPL42) were common between oligospermia and teratospermia." (PMID 29150651, 2017).
glioma (1 paper, 2022). A benign or malignant brain and spinal cord tumor that arises from glial cells (astrocytes, oligodendrocytes, ependymal cells). "BIRC3, KLHL10 and RNF135 showed unfavorable biomarker performance in glioma samples, and only RNF185 may serve as a favorable marker." (PMID 35183197, 2022).
KLHL10 also shares sentences with these, for which no sentence is quoted: asthenozoospermia (1 paper); cancer (1); teratospermia (1).